GSK3B (glycogen synthase kinase 3 beta)
Diseases named in the same sentence as GSK3B in open-access papers (continued):
Sharing a sentence is not in itself a finding about the gene and the disease.
diabetes (228 papers, 2005 to 2025). "Dysregulation of GSK-3β is associated with various diseases, including diabetes, obesity, and neurodegenerative diseases (Sayas and Ávila, 2021)." (PMID 40469843, 2025). "Herein, we investigated the role of REDD1-dependent GSK3β signaling in the activation of canonical NF-κB signaling in renal inflammation caused by diabetes." (PMID 39880090, 2025). "GSK3B's activity is tightly regulated by phosphorylation, and its dysregulation is associated with multiple diseases, including diabetes and cancer." (PMID 40919176, 2025). "In our study, our focus was to investigate the molecular interactions between myricetin and key regulators implicated in diabetes, including glycogen synthase kinase 3 beta (GSK3β), insulin receptor (IR), and glucose kinase (GCK)." (PMID 38465169, 2024). "Both types of diabetes are associated with central changes in the insulin/PI3K/Akt pathway that alter the phosphorylation of glycogen synthase kinase-3β (GSK3β) to promote excess phosphorylation of the microtubule-associated protein tau." (PMID 38416718, 2024). "Diabetes and obesity share common mechanisms modifying AD risk, such as IR-mediated GSK3β activation, AGE-mediated Aβ production and peripheral inflammation-mediated neuroinflammation." (PMID 38290839, 2024). "Glycogen synthase kinase-3β (GSK3β) is a pivotal protein kinase implicated in a spectrum of debilitating diseases, encompassing cancer, diabetes, and neurodegenerative disorders." (PMID 38168595, 2024). "Our previous multicenter case-control study showed that aging, up-regulation of platelet glycogen synthase kinase-3β (GSK-3β), impaired olfactory function, and ApoE ε4 genotype were associated with cognitive decline in type 2 diabetes mellitus (T2DM) patients." (PMID 38660514, 2024). "Several signaling pathways are implicated in diabetes, including those involved in cell stress such as GSK3β and ERK1/2." (PMID 35880011, 2022). "Originally discovered as a regulator of glycogen metabolism, GSK3β has since been implicated in neural development as well as pathological processes associated with chronic diseases including diabetes, neurodegeneration, and cancer (see reviews)." (PMID 36362354, 2022). "It has been reported that GSK-3β is a potential link between diabetes and AD; the excessive activation of GSK-3β can cause hyperphosphorylation of tau." (PMID 32774301, 2020). "The present study demonstrates for the first time that loss of β-catenin due to GSK3β activation triggers RGCs synaptic neurodegeneration by inducing oxidative stress-driven mitochondrial damage in HFD-induced diabetes." (PMID 32575075, 2020). "Hyperactivity of GSK3β has been implicated in secondary effects of diabetes in the kidney and retina." (PMID 30978208, 2019). "To further investigate the role of PI3K/Akt/GSK-3β in diabetes-associated cognitive impairments, we used LY." (PMID 28584284, 2017). "Our findings suggest that atorvastatin attenuates diabetes-associated renal injury by reducing ROS generation, RhoA activity and normalizing Akt/GSK3β signaling pathways." (PMID 27649495, 2016). "We found that although Zn deficiency or diabetes alone slightly decreased (P<0.05), diabetes with Zn deficiency further decreased, the phosphorylation of Akt and GSK-3β." (PMID 23251339, 2012). "STZ-induced diabetes caused alterations in pathways upstream of GSK-3β, such as PI3K, Jak/STAT, and MAPK pathways, limiting the cardioprotective effects of morphine administered at reperfusion." (PMID 22462028, 2012). "A previous study in IRS2 null mice had demonstrated that the severe diabetes associated with markedly increased apoptosis and reduced proliferation of islet β-cells was reversed when crossed with Gsk3β haploinsufficient mice." (PMID 21541314, 2011). "The implication of GSK3β in circadian control is significant, especially considering that this kinase has been linked to various diseases such as diabetes, Alzheimer's, cancer and neuropsychiatric disorders." (PMID 20049328, 2010).
diabetes (continued). "GSK3β has been linked to various pathological conditions such as diabetes, Alzheimer's, cancer and bipolar disorder." (PMID 20049328, 2010). "Finally, in a recent study, our team provided the first evidence for the implication of GSK3β in diabetes-associated islet inflammation." (PMID 36499613, 2022). "In conclusion, the decrease in insulin/Igf signaling induces Foxo1 and Gsk-3β function, resulting in impaired replication and enhanced β-cell death at transcription and protein levels, respectively, ultimately leading to postnatal β-cell loss and diabetes." (PMID 36361703, 2022). "Furthermore, XTZK notably inhibited the progression of Qi and Yin deficiency syndrome in diabetes through the mediation of the Akt/GSK-3β axis." (PMID 36588590, 2022). "Overexpression or abnormal activation of GSK3-β was associated with type 2 diabetes mellitus." (PMID 33672704, 2021). "In the brain, GSK3β regulates many aspects of cellular structure, function and survival, and its activity has been associated with the compromise of functional outcomes in different models of disease, including diabetes." (PMID 34948265, 2021). "Also, a genetic mutation of the Gys inhibiting enzyme Gsk3β (that renders Gsk3β resistant to IIS inhibition) corrected diabetes in mouse models of insulin resistance and protected against metabolic syndrome." (PMID 30537423, 2019). "GSK-3β, an important intracellular protein known as downstream of the Akt pathway, also linked with oxidative stress and cell apoptosis and exert a key role in diabetes mellitus." (PMID 30402501, 2018). "Interestingly, the activities of members of the RISK pathway, including Akt, ERK1/2, and GSK-3β, are often impaired in conditions of diabetes, obesity, insulin resistance, and hypercholesterolemia." (PMID 26788246, 2016). "Activation of GSK3β in the mouse forebrain reversibly induces tangles, astrocytosis, and learning deficiencies, while inhibition of GSK3β overcomes cognitive decline associated with diabetes." (PMID 26521867, 2016). "Since diabetes, linked itself to dysregulation of GSK3β activity, is associated in late-life with an increased risk of dementia, epidemiological and experimental studies are summarized in this issue in order to understand the effects of diabetes mellitus on tau pathogenesis." (PMID 25538567, 2014). "Hence, impaired insulin and IGF-1 signaling resulting in decreased GSK-3β (Ser 9) expression allows for phosphorylation of p-GSK-3β, a potent phosphorylating stress kinase, which has also been implicated in Alzheimer-like changes in diabetes." (PMID 19834568, 2009). "Molecular docking prediction studied results showed that all 27 active compound molecules from mango leaves could bind to the key interacting residues of 3 diabetes-causing enzymes, including GSK3β, DPP-4, and GLP-1R with the promising binding affinities (Table A1)." (PMID 41465578, 2025). "Thus, interventions targeting REDD1 or GSK3β in the context of nephropathies linked to metabolic illnesses like diabetes could potentially improve the current standard of care." (PMID 39880090, 2025). "Similarly, atorvastatin attenuated diabetes-associated renal injury by reducing Nox4-induced ROS production and RhoA activity and by normalizing Akt/glycogen synthase kinase 3 beta (GSK3β) signaling pathways, which are known to be important players in renal pathology." (PMID 37242602, 2023). "Therefore, we surmise that the activation of GSK3β found in these patients constitutes an additional link in the pathogenic chain that leads from increased [Ca2+]cyto to alteration in muscle utilization of glucose, then to hyperglycemia and diabetes." (PMID 36724092, 2023). "GSK3B is a multifunctional serine/threonine kinase, which is implicated in various biological activities such as metabolism, cell cycle, DNA damage repair, cell proliferation, and apoptosis, and is associated with diabetes, tumors, psychiatric and neurodegenerative diseases." (PMID 36743929, 2022).
diabetes (continued). "Several cardiac studies in diabetes also reported that hyperglycemia, insulin deficiency and insulin resistance were associated with loss of the conditioning-mediated cardioprotection and that this effect was driven by impaired signaling to Akt and GSK3β of the RISK pathway." (PMID 29872405, 2018). "However, loss of GSK-3β alone can rescue a mouse model of diabetes." (PMID 23185619, 2012). "Some antioxidant substances, such as liraglutide, Baicalin, and mango ginger extract, have been proved to alleviate oxidative stress of diabetes through the Akt/GSK3β/Fyn/Nrf2 signaling pathway." (PMID 40864777, 2025). "The study investigated the inhibitory potential of 27 compounds from M. indica leaves against three diabetes-related enzymes: GSK-3β, DPP-IV, and GLP-1R." (PMID 41465578, 2025). "Dysregulation of GSK-3β plays an important role in the pathogenesis of various diseases, including cancers, diabetes, and neuroinflammatory and neurodegenerative diseases." (PMID 41155719, 2025). "In the context of DN, elevated GSK3β expression has been observed within glomeruli of patients with diabetes and increased expression of GSK3β in urinary exfoliated renal cells from diabetic patients is a predictive biomarker of disease progression." (PMID 39880090, 2025). "We previously demonstrated that diabetes-induced REDD1 promotes renal oxidative stress and podocyte loss by suppressing the Nrf2 antioxidant response in a GSK3β-dependent manner." (PMID 39880090, 2025). "Increased expression of GSK3β has also been observed within podocytes in preclinical rodent models of diabetes and pharmacologic inhibition of GSK3β has shown promise in ameliorating diabetic kidney injury." (PMID 39880090, 2025). "This inhibition would lift the repressive effect of GSK-3β on glycogen synthase, promoting glycogen synthesis – a beneficial outcome for diabetes treatment." (PMID 41142063, 2025). "GSK3β activity is increased in the kidneys of diabetic patients and preclinical rodent models of diabetes." (PMID 39880090, 2025). "GSK‐3β, predominantly expressed in the liver, muscle, adipose tissue, and brain, is critically involved in the pathogenesis of diabetes, neurodegenerative diseases, and chronic inflammatory conditions." (PMID 40905109, 2025). "Another key enzyme involved in hepatic glycogen metabolism and affected in diabetes is glycogen synthase kinase-3β (GSK3β, EC 2.7.1.37)." (PMID 40806520, 2025). "Given that we only focused on the Akt/NF-ĸB and Akt/GSK-3β pathways in this study, further research into glabridin’s other mechanisms of action in preventing diabetes-related osteoporosis is needed." (PMID 40243576, 2025). "Fyn also plays a role in inflammatory stress-related signaling cascades such as the Akt/GSK-3β/Fyn/Nrf2 pathway, exacerbating inflammation in diabetes mellitus." (PMID 40864777, 2025). "Streptozotocin (STZ)-induced diabetes promoted activation of glycogen synthase kinase 3β (GSK3β) in the kidney, which was prevented by REDD1 ablation." (PMID 39880090, 2025). "The proof-of-concept studies here are consistent with a mechanism of action whereby REDD1 drives renal injury by promoting GSK3β-dependent NF-κB activation in podocytes, thereby enhancing the renal pro-inflammatory immune response to diabetes." (PMID 39880090, 2025). "In diabetes mellitus, OMVs impair insulin signaling and hepatic glycogen synthesis through gingipain-mediated disruption of the Akt/GSK-3β pathway." (PMID 40791780, 2025). "In a diabetic rat ulcer model, Astragalus polysaccharides stimulated macrophage polarization toward M2 by inhibiting GSK-3β, promoting β-catenin expression, and suppressing the NF-κB inflammatory pathway, thereby reducing the inflammatory response." (PMID 41158622, 2025). "Diabetes-induced changes in phosphorylation of GSK3β and GS in the kidney were attenuated in REDD1−/− mice." (PMID 39880090, 2025).
diabetes (continued). "This regulatory axis is particularly relevant in diabetes mellitus, where oxidative stress induces diminished Akt activation, leading to reduced inhibition of GSK3β." (PMID 40864777, 2025). "Consistent with the cell culture transwell migration assay, pharmacological inhibition of GSK3β by VP3.15 also reduced a diabetes-induced increase in F4/80 +ve and myeloperoxidase (MPO) +ve immune cell infiltration into glomeruli of diabetic mice." (PMID 39880090, 2025). "Mechanically, BBR inhibits ERS via GSK-3β and is thought to improve diabetes mellitus and glucolipid metabolism disorders induced by liver injury by blocking ERS by GSK-3β." (PMID 39791173, 2025). "Western blotting indicated that both Akt2 expression and phospho-GSK3β (ser9), the inactive form of GSK3β, were decreased during diabetes." (PMID 38581667, 2024). "In the Akt/GSK-3β/tau signaling pathway, PBE inhibited diabetes-induced Akt inactivation, GSK-3β inactivation, and tau hyperphosphorylation." (PMID 38881175, 2024). "Experiments have shown evidence that attributes tau hyperphosphorylation, an AD biomarker, to PI3K/AKT/GSK3β signaling pathway damage due to diabetes mellitus." (PMID 39767690, 2024). "Multiple markers like phosphorylated insulin receptor substrate 1(p-IRS), protein kinase B (p-Akt) and phosphorylated glycogen synthase kinase-3 beta (p-GSK3β) are quantified for the insulin resistance and diabetes mellitus in this study." (PMID 39281480, 2024). "In our study, PBE reduced diabetes-induced increased tau phosphorylation by regulating Akt/GSK-3β, which is consistent with previous studies." (PMID 38881175, 2024). "This study aimed to investigate the neurotherapeutic effects of quercetin-loaded nanoparticles (Q-LNP) and BCA extracted from TA against diabetes-induced cerebral cortical damage through modulation of PI3K/Akt/GSK-3β and AMPK signaling pathways." (PMID 38683825, 2024). "Our goal was to use MD analysis to look at the interactions between IR, GSK3β, and GCK, three important proteins implicated in diabetes, and their regulatory activity." (PMID 38465169, 2024). "We did not conduct glucose tolerance test, the classic test used to diagnose diabetes, and only some of the PI3K/Akt signaling pathways (Akt/GSK-3β) of diabetes were evaluated." (PMID 38881175, 2024). "Type 2 diabetes is one of the main health problems worldwide and the GSK‐3β/Fyn/Nrf2 signaling pathway is a target for diabetes treatment." (PMID 37823118, 2023). "This alteration in the effect of postconditioning is a consequence of the remodeling caused by the diabetes which blocks or impairs activation of many kinases including, among others, PI3 kinase/Akt, ERK, p70S6 kinase, and/or GSK-3β." (PMID 37259385, 2023). "The second link to diabetes is the observed activation, again by proteolysis mediated by the activated calpain, of GSK3β." (PMID 36724092, 2023). "We observed increased REDD1 expression in the retina of mice after 16 weeks of streptozotocin (STZ)-induced diabetes and found that REDD1 was essential for diabetes to suppress inhibitory phosphorylation of glycogen synthase kinase 3β (GSK3β) at S9." (PMID 37392853, 2023). "This study provides evidence that GSK3β inhibition reduces vascular calcification in diabetes mellitus." (PMID 36983045, 2023). "These proof-of-concept studies support that diabetes-induced REDD1 expression promotes dephosphorylation of GSK3β and consequently retinal inflammation." (PMID 37392853, 2023). "GSK-3β and Nrf2 have emerged as promising therapeutic targets for treating chronic diseases including several nervous system disorders and diabetes, due to their role in the cellular response to oxidative stress." (PMID 36979006, 2023). "The link between the high activity of GSK3β and diabetes in human skeletal muscle is well established, as is the therapeutic potential of GSK3β inhibitors." (PMID 36724092, 2023).
diabetes (continued). "GSK-3β has emerged as one of the potential drug targets for an array of diseases ranging from cancer to diabetes, polycystic kidney disease, and AD." (PMID 38022801, 2023). "Studies here identify a role for REDD1-dependent GSK3β activation in regulation of NF-κB signaling and the inflammatory response of the retina to diabetes." (PMID 37392853, 2023). "Disrupted insulin signaling in diabetes affecting the GSK-3β pathway can lead to excessive tau phosphorylation, increasing the risk of Alzheimer’s." (PMID 38002034, 2023). "REDD1-dependent dephosphorylation of GSK3β was observed throughout the retinal layers in response to diabetes, which is consistent with localization to Müller cells." (PMID 37392853, 2023). "Several other kinases are known to be activated in diabetes and it is possible that GSK3β is only one of the mechanisms that triggers ADAM10 and 17 upregulation." (PMID 37762417, 2023). "Diabetes promoted NF-κB activation, enhanced proinflammatory cytokine expression, and led to retinal immune cell activation in a manner that required GSK3β activity." (PMID 37392853, 2023). "A particular focus is on GSK-3β, a protein kinase that is at the interface between tau phosphorylation, AD and diabetes mellitus." (PMID 37034173, 2023). "The elevation of GSK‐3β activity was positively correlated the diabetes duration, as well as plasma glycated hemoglobin (HbA1c) and glucose levels." (PMID 37700547, 2023). "Collectively, the findings support a model wherein diabetes enhances REDD1-dependent activation of GSK3β to promote canonical NF-κB signaling and the development of retinal inflammation." (PMID 37392853, 2023). "Overall, the findings support a model whereby diabetes-induced REDD1 expression acts to promote retinal inflammation by GSK3β-dependent activation of IKK and thus increased canonical NF-κB signaling." (PMID 37392853, 2023). "It has been established that HOTAIR is involved in hepatic insulin resistance via inhibiting sirtuin 1 (SIRT1), a potential therapeutic target to combat insulin resistance and diabetes, and suppressing the/Akt/glycogen synthase kinase-3β (GSK-3β) pathway." (PMID 35359879, 2022). "Here, we have demonstrated that the reduced IR and IRS1 protein levels are attributable to not only the increased expression of MG53 but also the elevated phosphorylation at S255 by GSK3β in the context of diabetes." (PMID 36337049, 2022). "By inhibiting GSK-3β and affecting oxidative stress, apoptosis, calcium overload, and mPTP opening, DEX preconditioning presumably shields the myocardium from diabetes-induced activation of GSK-3β-mediated pathogenic effects." (PMID 36120296, 2022). "As GSK-3β is a promising target for diabetes therapy, glucose uptake effects of meridianin C and its analogues were evaluated for their potent kinase inhibitory activity toward GSK-3β." (PMID 36557848, 2022). "The findings from this study confirmed that the treatment with SAL ameliorated DN in rats with STZ-induced diabetes by inhibiting oxidative stress and inflammation via Akt/GSK-3β signalling pathway." (PMID 36086879, 2022). "Our data support the premise that Akt2 cKO in the RPE has a protective effect against diabetes-induced retinal damage, including infiltration and activation of immune cells, by mediating the Akt1/GSK3β/NF-κB signaling axis." (PMID 36229454, 2022). "GSK3β is a key enzyme of glycogen synthesis, and is elevated in both human subjects and animal models with diabetes." (PMID 35382381, 2022). "Induction of diabetes decreased the ratio of phospho-GSK3β/GSK3β, and increased the proportion of phospho-NF-κB p65/NF-κB p65 in the RPE of Akt2fl/fl diabetic mice compared to Akt2fl/fl nondiabetic controls." (PMID 36229454, 2022). "Due to its major role in several cellular processes, changes in GSK3B expression and function are strongly related to several aging-related diseases such as diabetes, cancer, inflammatory conditions, and neurodegenerative disorders." (PMID 35205276, 2022).